TLR4 (toll like receptor 4)
Diseases named in the same sentence as TLR4 in open-access papers (continued):
Sharing a sentence is not in itself a finding about the gene and the disease.
malaria (continued). "On the whole, the objective of current study was to assess the role of TLR4 (D299G, T399I) and TLR9 (T1237C, T1486C) in severity or susceptibility of malaria by meta-analysis of data from eligible studies." (PMID 34217314, 2021). "Individual studies showed the role of TLR4 (D299G) or TLR 9 (T1237C, T1486C) genetic polymorphisms on the occurrence/progression of malaria, while other studies had reported differently." (PMID 34217314, 2021). "This study aimed to assess the role of TLR4 (D299G, T399I) and TLR9 (T1237C, T1486C) in severity or susceptibility of malaria by meta-analysis of data from eligible studies." (PMID 34217314, 2021). "The association of TLR 4/TLR 9 and severity of malaria was reported in nine studies for TLR9 (T1237C), eight studies for TLR9 (T1486C), ten studies for TLR4 (D299G) and five studies for TLR4 (T399I)." (PMID 34217314, 2021). "TLR-2 and TLR-4 have been considered important in the development of the inflammatory response and pathology in several infectious diseases, such as tuberculosis, malaria, and toxoplasmosis." (PMID 33194814, 2020). "More recently, AS01, an adjuvant composed by two immunostimulants, (saponin QS21 and monophosphoryl lipid A, targeting TLR4), has been licensed for a vaccine against malaria and herpes zoster vaccine." (PMID 32582169, 2020). "We used this experimental setting to analyze inflammatory mediators known to be involved in the host response to malaria parasites, namely, Toll-like receptor 4 (TLR4) and type I interferon receptor 1 (IFNAR1)." (PMID 29440369, 2018). "We first confirmed previous reports showing that CD36 acts as a phagocytic receptor in the internalization of malaria parasites and that TLR4 is a receptor involved in the phagocytosis of E. coli by macrophages." (PMID 30158654, 2018). "It has been reported that CD36 is a receptor involved in the phagocytosis of malaria parasites and TLR4 in the phagocytosis of E. coli." (PMID 30158654, 2018). "Using a mouse model for placental malaria infection, our study aimed to evaluate the detrimental effects of the severe inflammatory response via TLR4 signalling in the pathogenesis of malaria during pregnancy." (PMID 28819109, 2017). "Even though the GPI-induced immune response is widely described to be mediated by pattern recognition receptors such as TLR2 and TLR4, previous studies have revealed that these two receptors are dispensable for the development of severe malaria pathology." (PMID 28560184, 2017). "Most results normalized in convalescence with the notable exception of pro‐inflammatory cytokine‐producing cells in SMA, and TLR‐2 and TLR‐4 expression during convalescence from all forms of malaria." (PMID 27027867, 2016). "In convalescence, the expression of TLR‐2 and TLR‐4 was lower in all three clinical forms of malaria compared to levels observed in acute disease, but this difference was only significant in the UM group." (PMID 27027867, 2016). "The role of free heme in EPC depletion during severe malaria pathogenesis is poorly understood; therefore we explored the possibility that depletion of these endothelial cell precursors is mediated by TLR4." (PMID 26555697, 2015). "The present study has examined the role of the two non-synonymous SNPs, rs4986790 (Asp299Gly) and rs4986791 (Thr399Ile), located at the third exon of the TLR4 gene in the development of clinical and severe malaria among children with Yoruba ethnic background." (PMID 27350800, 2015). "EPC numbers were significantly decreased in malaria patients (P < 0.02) and TLR4 expression was significantly elevated in vivo." (PMID 26555697, 2015). "Decreases in EPC were associated with increased heme and CXCL10 levels in addition to increased expression of TLR4 in malaria patients." (PMID 26555697, 2015).
malaria (continued). "We have shown that decreased bioavailability of EPC in malaria patients is due, in part, to heme toxicity, mediated by expression of TLR4 and further exacerbated by an exaggerated host inflammatory response due to excess production of CXCL10." (PMID 26555697, 2015). "Comparisonwith other malaria endemic populations suggestsdifferent local evolutionary pressures on TLR4 polymorphismsby malaria or other infectious diseasein this region." (PMID 23862121, 2013). "Therefore,it seems that the study of these two TLR4 SNPs in theco-segregate state in different populations from variousmalaria endemic regions might aid understandingof the correlation of TLR4 polymorphisms withclinical malaria as well as other infectious diseases." (PMID 23862121, 2013). "Our findingsmight support their report, as the frequencyof the TLR4 Asp299Gly/Thr399Thr genotype wasobserved to be significantly lower in Baluchi individualswith mild malaria." (PMID 23862121, 2013). "In severe malaria cases, patients show increased surface expression of TLR4 on innate immune cells (monocytes and dendritic cells)." (PMID 23967200, 2013). "But in European populations,where the malaria pressure is lower thanin the African population, the TLR4 Asp299Gly/Thr399Ile genotype is more prevalent." (PMID 23862121, 2013). "Together, the genetic data support a role for TLR4 in modulating the presentation of malaria symptoms." (PMID 22615793, 2012). "The expression of TLR2 was lower on both monocytes (8 out of 11 subjects) and neutrophils (10 out of 11 subjects) from malaria patients, whereas expression of TLR4 was only affected on neutrophils (8 out of 12) from infected individuals." (PMID 22745844, 2012). "This study was planned to make a further contribution to solving the problem of the real role of the most common polymorphisms of TLR4, TLR9, TIRAP and FCGR2A in modulating the risk of malaria and disease severity." (PMID 22691414, 2012). "For instance, polymorphisms in TLR1, TLR4 and TLR9 are associated with an aggravated clinical status of malaria during pregnancy." (PMID 22096530, 2011). "The adaptor protein tirap S180L SNP (rs8177374) has been reported to diminish TLR-2 and TLR-4 signaling and heterozygosis for this SNP has been claimed to confer protection against mild and severe malaria to an extent comparable to HbAs." (PMID 21457584, 2011). "TLR2, TLR4, TLR9, and downstream signaling pathways of these proteins have recently been implicated in human malaria pathogenesis." (PMID 19317913, 2009). "This study focused on TLR2, TLR4, TLR9 and MAL because these genes have been implicated in human malaria pathogenesis." (PMID 19317913, 2009). "Both TLR4 Asp299Gly and TLR9 -1486T/C were associated with low birth weight and maternal anaemia in a malaria endemic population." (PMID 19317913, 2009). "Therefore, this study aimed to analyse the potential influence of variants of TLR1, TLR4, TLR7, TLR8, TLR9 and TIRAP on the clinical manifestations of malaria caused by P. vivax in the Amazon region of Brazil." (PMID 40963451, 2025). "Further, due to limited cell numbers in malaria naive donors, we were also unable to investigate the specific innate cell pathways linked to differences seen following parasite simulation (for example, TLR2 or TLR4 pathways)." (PMID 41027884, 2025). "Despite these limitations, our findings indicate that variants of TLR4 and TLR9 may be molecular markers for the clinical presentation of malaria caused by P. vivax in the admixed population of the Brazilian Amazon." (PMID 40963451, 2025). "For other polymorphisms, such as TLR 4 (D299G) and TLR4 (T399I), none of the five genetic models show significant association with severity of malaria." (PMID 34217314, 2021).
malaria (continued). "For TLR4 (D299G, T399I), none is significantly associated with either severity of malaria or susceptibility to malaria under any genetic models." (PMID 34217314, 2021). "The role of TLR4 in malaria during pregnancy has also been examined in genetic association studies." (PMID 31178840, 2019). "After controlling for autocorrelation, SNP 5239s1 was still associated with malaria risk (estimate = 0.38, SE = 0.17, p = 0.030) but TLR4_2 was not (p = 0.423)." (PMID 31788192, 2019). "Three other loci (CR1, TNF, and TLR4) showed borderline associations with the principal component 2 but not with any particular measure of malaria transmission." (PMID 28541483, 2017). "Our findings indicate that the two minor alleles 299 Gly and 399Ile of TLR4 SNPs are not protective against severe malaria in the studied children." (PMID 27350800, 2015). "Among them, TLR4 has been suggested to be protective against malaria in certain populations." (PMID 26099491, 2015). "Unlike in asymptomatic population, the genotype distribution of TLR4 Asp299Gly polymorphism was not in HWE in the clinical malaria group but did not condition susceptibility." (PMID 27350800, 2015). "Unlike in asymptomatic population, the genotype distribution of TLR4 Asp299Gly SNP was not in HWE in the clinical malaria group but did not condition susceptibility." (PMID 27350800, 2015). "FACS analysis was used to determine whether EPC exhibited altered expression of TLR4 in non-malaria versus malaria subjects." (PMID 26555697, 2015). "Here we propose a TLR4-mediated role by which mature EPC are reduced in malaria patients." (PMID 26555697, 2015). "This hypothesisneeds to be supported by analyzing TLR4 polymorphismsin more samples from diverse malaria hypoendemicregions." (PMID 23862121, 2013). "TLR4 variants have been shown to increase the risk to septic shock, Gram-negative infections as well as severe malaria in children." (PMID 24312262, 2013). "This study was planned to make a further contribution to solving the problem of the real role of the most common polymorphisms of TLR4, TLR9, TIRAP and FCGR2A genes in modulating the risk of malaria and disease severity in children from Burundi, Central Africa." (PMID 22691414, 2012). "TLR9 T1237C seems to condition susceptibility to malaria in Burundian children but not its severity, whereas none of the assessed SNPs of TLR4, TIRAP and FCGR2A seem to influence susceptibility to malaria and disease severity in this population." (PMID 22691414, 2012). "They found that a common tlr-4 D299G increases the risk of severe paediatric malaria without affecting on the risk of infection." (PMID 21457584, 2011). "Befitting any general immune response mechanism, various cytokines may potentially modulate ICAM1 expression, of which we have found evidence for statistical association of IL1, IL4 (and its receptor, IL4R), IL6, IL13, TLR2, TLR4, and IFNG (and its receptor, IFNGR1) polymorphisms with malaria." (PMID 37287037, 2023). "This supports the current literature pertaining to the disease, as well as suggests that further research into the role of TLR4, as well as other related genes, in pathogenesis of clinical malaria may provide further insight into drug development and treatment of the disease." (PMID 37287037, 2023). "TLR4 and its immune-related signalling pathways have been reported to contribute significantly to P. falciparum growth and malaria pathogenesis, such that dysregulation and dysfunction of the gene increase malaria severity, symptomatic malaria, severe malaria anaemia, and resistance in Africa." (PMID 34702263, 2021). "They had no impact on prematurity, viability or the incidence of placental malaria, suggesting that maternal TLR4 takes part in responding to infection, but may not be linked to severe placental dysfunction during malaria." (PMID 31178840, 2019). "No other TLR4 protein haplotypes showed associations with malaria risk." (PMID 31788192, 2019).
malaria (continued). "Here, we used an experimental genetic heterogenic system where homozygous primigravid mice carry heterozygous fetuses, aiming to discern whether the expression of TLR4 and IFNAR1 molecules in either maternal or fetal compartments is implicated in outcomes of malaria in pregnancy." (PMID 29440369, 2018). "Single nucleotide polymorphisms (SNPs) in TLR4 (A299G and T399I) were shown to be associated with the onset of clinical manifestations of severe Pf-malaria in African children and pregnant women, and in adults with non-severe symptomatic malaria." (PMID 28850598, 2017). "Therefore, our results implicate that TLR4 blockage could be a potential candidate for therapeutic interventions to reduce malaria-induced pathology both in the mother and the fetus." (PMID 28819109, 2017). "Thus, the observation that the expression of both TLR‐2 and TLR‐4 in convalescence of all malaria types was even lower than that observed in acute infection could be a result of such tolerance which could take longer than 30 days to dissipate." (PMID 27027867, 2016). "This resultsuggests that different TLR4 Asp299Gly/Thr399Ileco-segregating genotypes might not be associatedwith mild malaria in our studied population." (PMID 23862121, 2013). "In analogy to bacterial infections, TLR4 polymorphisms may reduce responsiveness to P. falciparum and to GPI in particular and thus cause severe malaria due to both inadequate innate responses at disease onset and insufficient stimulation of specific immunity during preceding infections." (PMID 24312262, 2013). "In addition, the frequency of the common TLR4 co-segregategenotypes was compared between the Baluchipopulation who are living in malaria hypoendemicareas of Iran with those reported results from otherpopulations from similar or contrasting malariasettings around the world." (PMID 23862121, 2013). "Whereas MAL Ser180Leu and the TLR4 SNPs in other populations have respectively, been associated with protection and susceptibility to malaria, these associations may not exist in the Kenyan or Papua New Guinean populations examined here." (PMID 19317913, 2009). "Indeed, data presented here suggests that increased frequencies of cells producing inflammatory cytokines in response to malaria parasites may be mediated by increased TLR4 activation, which was transcriptionally activated in monocytes in adults and not children in response to parasite stimulation." (PMID 41027884, 2025). "Known PAMPs in malaria include Plasmodium glycosylphosphatidylinositols (GPIs) that bind avidly to TLR2 and less stringently to TLR4." (PMID 39452740, 2024). "The interaction between the TLR4 and adjuvant enhance the immune response, while TLR3, TLR4 and TLR9 agonists have been used to improve vaccines against HBV, influenza, malaria and anthrax." (PMID 35371033, 2022). "Malaria is an infectious disease that also requires TLR1/2, TLR4, and TLR6 to form an immune response." (PMID 36313452, 2022). "Studies have shown that malaria GPI is sensed by TLRs on the surface of macrophages or DCs, mainly through the TLR1-TLR2 heterodimers and TLR4." (PMID 33344264, 2020). "TLR4 and TLR9 are strongly activated by malaria parasite PAMPs such as glycosylphosphatidylinositol (GPI), DNA, and hemozoin." (PMID 33013876, 2020). "We show that CD16+ DCs respond to TLR1/2 and TLR4 stimulation with robust TNF production both before and during induced blood-stage malaria." (PMID 30239833, 2019). "We have investigated the role of TLR4 and IFNAR1 in malaria during pregnancy, with a focus on dissecting the contributions of maternal and fetal compartments to pregnancy outcomes." (PMID 29440369, 2018). "DNA and RNA play prominent roles in mouse malaria immunity and pathogenesis; under certain conditions TLR2 and TLR4 also play important roles." (PMID 30619355, 2018).
malaria (continued). "As such, studies in various mouse models have demonstrated that TLR9, TLR7, TLR4, and TLR2 play important roles in malaria immunity and cerebral, placental and other severe malaria pathology." (PMID 30619355, 2018). "Within the malaria pathway, miR-146a suppresses the CD40L, CXCL8, IFNγ, TLR2, TLR4, and ITGβ2 genes." (PMID 29747626, 2018). "Taken together, MRP14 can be involved in the pathology of hepatic injury during malaria through activation of TLR2 and TLR4 signaling." (PMID 29902248, 2018). "We conducted this study to explore expression of CD11a, CD11b, CD11c, CD18, HLA‐DR, CD86, TLR‐2 and TLR‐4 and production of TNF‐α and IL‐6 by monocytes in Malawian children presenting with different clinical forms of malaria." (PMID 27027867, 2016). "Patients with severe and mild malaria also showed increased surface expression of TLR2 and TLR4 on CD14+ monocytes and cDCs and decreased intracellular expression of TLR9 on pDCs." (PMID 27716849, 2016). "The leishmaniasis pathway had three probes in common with malaria (TLR2, TLR4, CR1), while Staphylococcus aureus infection had one (CR1)." (PMID 26961973, 2016). "The TLR probes showed a higher expression in severe malaria cases during acute illness (2.07-fold for TLR2, 2.19-fold for TLR8, 2.27 and 2.46-fold for the TLR4 probes)." (PMID 26961973, 2016). "Differentially expressed probes form these canonical pathways that were previously shown to play a role in severe malaria pathogenesis were TLR2, TLR4, TLR8, HSPA6, CR1, C1qA, C1qB, C1qC, FOS, and GZMB." (PMID 26961973, 2016). "TLR probes showed a higher expression in severe malaria cases during acute illness (2.07-fold for TLR2, 2.19-fold for TLR8, 2.27 and 2.46-fold for TLR4 probes)." (PMID 26961973, 2016). "For example, the KEGG term “Malaria” is enriched in the UP genes in RA due to genes such as CR1, GYPA, ICAM1, PECAM1, and TLR4." (PMID 28491277, 2016). "We have shown that integral components of the BBB, specifically HBVEC and CD34+-HSPC, are activated to increase expression of TLR4 in addition to excess CXCL10 production in the presence of increased heme, which mimics in vivo conditions in malaria." (PMID 26555697, 2015). "In particular, TLR3, TLR4 and TLR9 agonists have been shown to improve a number of vaccines, for example against HBV, influenza, malaria and anthrax, as well as some types of cancer." (PMID 26344622, 2014). "The list of TLR ligands now includes malaria-derived molecules: Pf toxin, glycosylphosphatidylinisitol is recognized by TLR2 and TLR4, whereas parasite DNA complexed with haemozoin is a TLR9 ligand." (PMID 19691558, 2009). "In a mouse model of malaria, we tested R21 with two liposomal adjuvants (LQ, LMQ) and two squalene emulsion adjuvants (SQ, SMQ), all containing saponin QS-21, and LMQ and SMQ additionally supplemented with a synthetic MPL-like TLR4 agonist." (PMID 37913775, 2023). "This was the first work to describe non-canonical pyroptosis activation in malaria, in a TLR4-independent process, although its role in the pathogenesis of malaria is more limited than the canonical pyroptosis." (PMID 33672278, 2021). "TLR4-299G without linkage with TLR4-399T can be found among African populations and is reported to be protective against malaria." (PMID 33557133, 2021). "TLR1, TLR2, TLR4, TLR6, TLR7 and TLR9 have been reported to recognize malaria ligands." (PMID 33344264, 2020). "In mice, TLR4 has been implicated in dendritic and mast cell activation during malaria, potentially contributing to the resistance of DBA/2 mice to infection with P. yoelii, although TLR4 has not been linked to the pathology of experimental cerebral malaria." (PMID 31178840, 2019). "However, in several infectious diseases, such as tuberculosis, malaria, and toxoplasmosis, TLR2 and TLR4 have been considered important in the development of the inflammatory response and pathology." (PMID 31119102, 2019).